RN7SKP169 (RN7SK pseudogene 169)
Gene: Miscellaneous RNA gene on chromosome 22 (25,963,983 to 25,964,273, reverse strand). Ensembl gene ENSG00000223056.
Homologues: Orthologues: chimpanzee 7SK (99% identical). Paralogues in human: RN7SKP176 (75% identical), RN7SKP250 (73% identical), RN7SKP189 (73% identical), RN7SKP47 (73% identical), RN7SKP245 (72% identical), 7SK (72% identical), RN7SKP124 (72% identical), RN7SKP162 (72% identical), RN7SKP217 (72% identical), RN7SKP255 (72% identical), RN7SKP79 (72% identical), RN7SKP90 (71% identical), and 284 more.